PLOD1 (procollagen-lysine,2-oxoglutarate 5-dioxygenase 1)
Diseases named in the same sentence as PLOD1 in open-access papers (continued):
Sharing a sentence is not in itself a finding about the gene and the disease.
Cognitive impairment (1 paper, 2026). Abnormal cognition is characterized by deficits in thinking, reasoning, or remembering. "Of the top 10 most significant proteins, six (PLOD1, MFN2, NGFR, PPP2R5E, C4A/C4B, and ITGAV) have previously been linked to AD and/or cognitive function, underscoring their potential as biomarkers of cognitive impairment." (PMID 42253369, 2026).
colon cancer (1 paper, 2020). "A subset of ECM glycoproteins, such as thrombospondin-2 (THBS2), ECM regulators including lysyl oxidase homolog 2 (LOXL2) or procollagen-lysine,2-oxoglutarate 5-dioxygenase 1 (PLOD1), and affiliated proteins such as MUC13 have been specifically identified in colon cancer samples." (PMID 33297478, 2020).
Down syndrome (1 paper, 2024). "Additional variants in the connective tissue-related COL11A, PLOD1, and FBN2 genes in disability patients may augment the hypermobility that results from CNS-related hypotonia as reported in a child with Down syndrome." (PMID 38534782, 2024).
intrahepatic cholangiocarcinoma (1 paper, 2025). A carcinoma that arises from the intrahepatic bile duct epithelium in any site of the intrahepatic biliary tree. "Univariate logit binomial analysis, with the outcome being the proliferative subclass status of intrahepatic cholangiocarcinoma, confirmed the significance of the probes for seven enzymes: FH, MAT2B, PLOD2, PLOD1, PDE6D, ALDOC, and NT5DC3." (PMID 40034261, 2025). "Based on the training and validation cohorts of intrahepatic cholangiocarcinoma (ICA) bulk transcriptomes, seven metabolic enzymes were confirmed to be overexpressed in cases with poor prognosis: FH, MAT2B, PLOD2, PLOD1, PDE6D, ALDOC, and NT5DC3." (PMID 40034261, 2025).
mesothelioma (1 paper, 2024). A usually malignant and aggressive neoplasm of the mesothelium which is often associated with exposure to asbestos. "There was a significant negative correlation (r ≤ −0.3) between PLOD1 expression and DNA methylation in UVM, LIHC, RAAD, UCS, SARC, mesothelioma (MESO) and pheochromocytoma and paraganglioma (PCPG)." (PMID 39767559, 2024).
myopia (1 paper, 2011). "In summary, we examined using a DNA pooling approach tag SNPs from four candidate genes (COL11A1, COL18A1, FBN1, and PLOD1) selected because pathogenic mutations in these genes cause disease syndromes that have myopia, usually high myopia, as one of the common presenting clinical features." (PMID 21527992, 2011). "In conclusion, common polymorphisms in these four candidate genes (COL11A1, COL18A1, FBN1, and PLOD1) were unlikely to play important roles in the genetic susceptibility to high myopia." (PMID 21527992, 2011).
nemaline myopathy (1 paper, 2024). Nemaline myopathy (NM) encompasses a large spectrum of myopathies characterized by hypotonia, weakness and depressed or absent deep tendon reflexes, with pathologic evidence of nemaline bodies (rods) on muscle biopsy. "In seven patients with nemaline myopathy, the authors identified several causal variants in the ACTA1 gene (in one patient), the LMOD3 gene (in two patients), the PLOD1 gene (in one patient), and the NEB gene (in four patients)." (PMID 37989827, 2024).
neutropenia (1 paper, 2017). A decrease in the number of neutrophils found in the blood. "rs1726801 (χ2 test P = 3.27 × 10−5; OR = 3.03, 95%CI:1.59–5.77, P = 0.001), rs1673041 (χ2 test P = 3.27 × 10−5; OR = 3.46, 95%CI:1.97–6.09, P = 1.70 × 10−5) and rs3219341 (χ2 test P = 3.09 × 10−5; OR = 3.03, 95%CI:1.59–5.75, P = 0.001) in PLOD1 were significantly associated with neutropenia." (PMID 28924235, 2017).
non-small cell lung carcinoma (1 paper, 2025). A group of at least three distinct histological types of lung cancer, including non-small cell squamous cell carcinoma, adenocarcinoma, and large cell carcinoma. "In patients with non-small cell lung cancer (NSCLC), the expression levels of PLOD1–3 and LOXL2—genes involved in collagen crosslinking—are significantly elevated in TECs compared to normal endothelial cells." (PMID 40721833, 2025).
sarcoma (1 paper, 2023). A usually aggressive malignant neoplasm of the soft tissue or bone. "The PLOD family includes PLOD1, PLOD2, and PLOD3, all of which may be linked to various cancers, including gastric cancer, sarcoma, and liver cancer." (PMID 36820030, 2023).
scoliosis (1 paper, 2022). A congenital or acquired spinal deformity characterized by lateral curvature of the spine. "Finally, one patient had a pathogenic PLOD1 variant and scoliosis but not connective tissue symptoms." (PMID 35918752, 2022).
triple-negative breast carcinoma (1 paper, 2024). An invasive breast carcinoma which is negative for expression of estrogen receptor (ER), progesterone receptor (PR), and human epidermal growth factor receptor 2 (HER2). "Besides, the levels of PLOD1, PLOD2 and PLOD3 were higher in triple negative breast cancer (TNBC) patients than non-TNBC patients." (PMID 39068670, 2024).
uterine carcinosarcoma (1 paper, 2024). A usually aggressive malignant neoplasm arising from the uterine corpus and less often the cervix. "Moreover, we found that the trend in PLOD1 gene mutation in SARC, uterine carcinosarcoma (UCS), SKCM, UCEC, KIRC, LUSC and GBM was consistent with its higher mRNA level." (PMID 39767559, 2024).
uveal melanoma (1 paper, 2024). A melanoma derived from melanocytes of the uveal tract. "The results showed that PLOD1 mRNA expression was mainly positively correlated with CNV, with uveal melanoma (UVM) being the most significant." (PMID 39767559, 2024).
cancer (52 papers, 2015 to 2026). A tumor composed of atypical neoplastic, often pleomorphic cells that invade other tissues. "Both external validation and IHC analysis consistently confirmed the associations of CBY1, CASP8, PLOD1, and several methylation sites (cg09907170, cg09395195, cg08129017, and cg14808739) with their corresponding cancers." (PMID 42052171, 2026). "The results showed that PLOD1 has a mutation frequency of <5% in the vast majority of cancers, except for CHOL, in which mutation and deep deletion are the main types of mutations." (PMID 39767559, 2024). "In our study, a robust anoikis-related model was developed based on the expression levels of three genes: EHBP1, CSPG4, and PLOD1.The presence of these three genes has been linked to a variety of malignant tumors." (PMID 39664392, 2024). "It has already been observed that PLOD1 mutations and overexpression promote the occurrence and metastasis of malignant tumors." (PMID 35454164, 2022). "With the development of genome and transcriptome sequencing, PLOD1 mutations have been found to be associated with a variety of cancers." (PMID 35265665, 2021). "In addition, immunosuppressive and immune-activating genes were strongly associated with PLOD1 expression in 33 cancers." (PMID 39767559, 2024). "However, the pan-cancer expression profile and diagnostic significance of PLOD1 remain incompletely characterized." (PMID 39767559, 2024). "In combination with the mRNA expression analysis of PLOD1, it can be concluded that in some cancers, abnormal expression of PLOD1 may be associated with genetic alterations and altered levels of DNA methylation." (PMID 39767559, 2024). "Therefore, in this study, we integrated information from multiple databases and characterized the expression profiles, prognostic value, genetic mutations and functional status of PLOD1 in 33 cancer types, focusing on its potential role in tumor immunology." (PMID 39767559, 2024). "In addition, PLOD1 encodes lysyl hydroxylases, which are crucial for collagen biosynthesis, cross‐linking, and deposition and can promote cancer progression and metastasis." (PMID 33292266, 2020). "Notably, PLOD1 expression correlated most strongly with cancer-associated fibroblasts, macrophage, NK cells, B cells and CD8+ T cells, suggesting a potential role in modulating stromal remodeling, macrophage recruitment and both innate and humoral immune response." (PMID 41142622, 2025). "In conclusion, our study demonstrates that PLOD1 can act as an oncogene in pan-cancer, is associated with the immune response and may constitute an emerging prognostic biomarker in multiple types of cancer." (PMID 39767559, 2024). "PLOD1 drives proliferation, migration, invasion, and therapy resistance in cancers by modulating pathways like β-catenin, NF-κB, and Akt/mTOR." (PMID 41373732, 2025). "First, our pan-cancer study on PLOD1 was limited to bioinformatics analyses and in vitro experiments and lacked large-scale patient cohort studies." (PMID 39767559, 2024). "It is hoped that this study provides new insights to promote the role of PLOD1 in the diagnosis and treatment of cancer." (PMID 39767559, 2024). "At the epigenetic level, the promoter methylation levels of PLOD1 were generally downregulated in a wide range of cancers." (PMID 39767559, 2024). "PLOD1 is highly expressed in many malignant tumors, likely contributing to the epithelial to mesenchymal cell transition in the course of cancer progression." (PMID 38640016, 2024). "We therefore integrated multigroup bioinformatics platforms and datasets to comprehensively analyze the pan-cancer characteristics of PLOD1." (PMID 39767559, 2024). "To understand the immunomodulatory function of PLOD1, we calculated the immune and stromal scores for PLOD1 in pan-cancer using the R package “ESTIMATE”." (PMID 39767559, 2024). "PLOD1 expression was associated with a decreased abundance of CD8+ T cells and B cells, among others, in a variety of cancers." (PMID 39767559, 2024).
cancer (continued). "We found that in 33 cancers, PLOD1 expression was negatively correlated with CD8+ T cells, B cells and CD4+ T cells, among others, and positively correlated with monocytes, macrophages, neutrophils and tumor-associated fibroblasts (CAFs)." (PMID 39767559, 2024). "Differential expression results showed statistically significant upregulation of PLOD1 expression in a total of 24 of 33 cancers compared to adjacent healthy tissues." (PMID 39767559, 2024). "To explore the co-expression network and enrichment pathway of PLOD1 in pan-cancer, we first predicted binding proteins for PLOD1 using the STRING website." (PMID 39767559, 2024). "It has been demonstrated that PLOD1 catalyzes lysyl hydroxylation and directly promotes collagen cross-linking and deposition, which ultimately leads to cancer and regulates cancer cell proliferation, apoptosis, invasion and migration." (PMID 39767559, 2024). "We have provided clues for further research on the specific mechanisms of PLOD1 in cancer progression and treatment." (PMID 39767559, 2024). "In this study, we aimed to elucidate the function and potential mechanism of action of PLOD1 across cancers." (PMID 39767559, 2024). "We next assessed its expression in the TCGA pan-cancer tissues, which showed that the PLOD1 expression was highest in SARC and lowest in kidney chromophobe (KICH)." (PMID 39767559, 2024). "In this study, data from The Cancer Genome Atlas (TCGA) and Genotype-Tissue Expression (GTEx) databases were used to analyze the role of PLOD1–3 in STS." (PMID 35627171, 2022). "PLOD1 has been reported to function in extracellular matrix formation and is involved in various diseases, including cancer." (PMID 33778011, 2021). "Our analysis revealed that 14 of 33 cancer types exhibited the highest mRNA expression of PLOD1 among the TCGA cohorts." (PMID 35265665, 2021). "With the development of genome and transcriptome sequencing technologies, genetic alteration of PLOD1 was found out to be closely related to various cancers." (PMID 33134376, 2020). "Through MTT and Transwell invasion assays, we confirmed the pro-cancer abilities of PLOD1 and PLOD2, which provided new basis for the molecular mechanism of RCC tumorigenesis." (PMID 33287763, 2020). "Other genes, such as CALCOCO2, RCAN2, ADI1, ECHS1, PLOD1 and VTI1B were associated with tumorigenesis or angiogenesis in some other cancers 33-35." (PMID 31632497, 2019). "In recent years, studies on PLOD1 mutations in cancer have been carried out, though not much has been reported." (PMID 39767559, 2024). "We then analyzed the prognostic significance of PLOD1 in cancer patients." (PMID 39767559, 2024). "Taken together, these findings indicate that PLOD1 may play an important role in different cancer types and subtypes." (PMID 39767559, 2024). "In summary, our study demonstrated that PLOD1 is commonly highly expressed in a wide range of cancers, which is accompanied by poor clinical prognostic outcomes, with an emphasis on the fact that we confirmed the complex relationship between PLOD1 and the tumor immune microenvironment." (PMID 39767559, 2024). "There is no doubt that PLOD1 plays an important role in cancer development, but the underlying mechanisms remain unclear." (PMID 39767559, 2024). "PLOD1/2/3 can catalyze the formation of hydroxylysine residues in the -Xaa-Lys-Gly- sequence in collagen, which can serve as an attachment point between collagen molecules and improve stability, and has recently been recognized as an important biomarker for cancer prognosis." (PMID 36572937, 2022). "In addition, another potential strategy is to reduce PLOD1 expression, this means that further understanding of the regulatory mechanism of PLOD1 in the development of cancer may lead to the exploration of novel signaling pathways to target PLOD1." (PMID 34040895, 2021). "Therefore, the present study may provide more reliable evidence that PLOD1 promoted in invasion of cancer cells." (PMID 33134376, 2020).
cancer (continued). "We analyzed the mRNA expressions of PLOD1, PLOD2, and PLOD3 in various cancer and normal tissues using Oncomine database." (PMID 39068670, 2024). "Three members of the PLOD family (i.e., PLOD1, PLOD2, and PLOD3) leading to cancer progression and metastasis when dysregulated have already been identified." (PMID 35250490, 2022). "Accumulating evidence has implicated members of the procollagen-lysine, 2-oxoglutarate 5-dioxygenase (PLOD) gene family, PLOD1, PLOD2, and PLOD3, in cancer progression and metastasis." (PMID 35265665, 2021). "PLOD1 and PLOD2 are the key enzymes of collagen synthesis and extracellular matrix formation, therefore can drive tumorigenesis and angiogenesis in many cancers." (PMID 33287763, 2020). "As a result, we ascertained that CD44, PLOD1 and PLOD2 played a pro-cancer role in RCC through vitro experiments, reiterating that glycolytic risk signature was closely associated with RCC progression." (PMID 33287763, 2020). "We also found that the expression of PLOD1 and PLOD2, members of procollagen-lysine, 2-oxoglutarate 5-dioxygenase (PLOD) superfamily, was overexpressed in multiple cancer types." (PMID 33287876, 2020). "A recent study showed a signature involving P4HA1, PLOD1, KDM3A, PLOD2, and ASPH predicted prognosis in various cancers including LUAD using bioinformatic analysis." (PMID 33299876, 2020). "Since the client protein and function of PLOD1, PLOD2, and PLOD3 in collagen synthesis are different, it is important to develop specific inhibitors for PLOD to halt cancer progression." (PMID 30003082, 2018). "Like PLOD2, PLOD1 is involved in collagen hydroxylation, and its upregulation in ICA suggests increased collagen synthesis, leading to a dense ECM, as demonstrated in other cancer types." (PMID 40034261, 2025). "PLOD1 is an iron-containing enzyme, which participates in the collagen assembly and in the regulation of collagen synthesis and extracellular matrix remodeling, consistent with the established role of MEMO1 in cancer cell tissue invasion and metastasis." (PMID 38640016, 2024). "Most previous studies have focused only on the role of PLOD1 in individual cancer types, and no pan-cancer analysis of the prognostic significance and biological function of PLOD1 has been performed thus far." (PMID 39767559, 2024). "PLOD1, PLOD2, and PLOD3 levels were upregulated in most cancers." (PMID 39068670, 2024). "Moreover, its hub genes (CD44, PLOD1 and PLOD2) were proven to possess pro-cancer abilities through MTT and Transwell invasion assays." (PMID 33287763, 2020). "The role of PLOD1 involved in the degradation of collagen and ECM construction might also play a crucial role in cancer metastasis." (PMID 33134376, 2020). "Immunostaining of PLOD1 in BC clinical specimens indicated high expression of PLOD1 in cancer lesions compared with adjacent noncancerous tissues at the same staining intensity." (PMID 31199049, 2019). "Finally, to avoid bias from patients who did not die from cancer, we also analyzed the relationship between PLOD1 expression and DSS." (PMID 39767559, 2024). "On the other hand, there are not many reports on the role of PLOD1 in cancer." (PMID 31199049, 2019). "Analysis of PLOD1, PLOD2, and PLOD3 mRNA expression in 20 cancer types (Oncomine dataset) showed significant upregulation and downregulation of the three PLOD isoforms in a number of cancers, including kidney cancer, compared with the corresponding normal tissues." (PMID 31446433, 2019). "HIF-1α induces the expression of P4HA1, P4HA2, PLOD1, and PLOD2 in different cancer and non-cancer cell lines, and enhanced activities of these enzymes are associated with increased collagen deposition in cancer tissue." (PMID 37490147, 2023).